GFRA1 (GDNF family receptor alpha 1)
Diseases named in the same sentence as GFRA1 in open-access papers (continued):
Sharing a sentence is not in itself a finding about the gene and the disease.
osteosarcoma (10 papers, 2017 to 2025). A usually aggressive malignant bone-forming mesenchymal neoplasm, predominantly affecting adolescents and young adults. "GFRA1 depletion inhibited the proliferation, DXR resistance, and autophagy of osteosarcoma cells, and the addition of anti-miR-381-3p counteracted the suppressive effects caused by GFRA1 depletion, suggesting that GFRA1 was a downstream functional target gene of miR-381-3p in osteosarcoma cells." (PMID 33817274, 2020). "Osteosarcoma sub-clones with elevated GFRα1 expression demonstrate increased motility, drug tolerance and mesenchymal marker expression; conversely, GFRα1 interference restores chemosensitivity." (PMID 41142827, 2025). "After treating osteosarcoma cells with cisplatin, a widely used anticancer drug, it induces the overexpression of GFRα1, which promotes autophagy to lead to enhanced osteosarcoma cell survival via the SRC-AMPK signaling axis." (PMID 35582425, 2022). "SNHG15 enhanced the DXR resistance of osteosarcoma cells through elevating the autophagy via targeting the miR-381-3p/GFRA1 axis." (PMID 33817274, 2020). "Meanwhile, the autophagy was restrained with GFRA1 depletion in osteosarcoma cells, and the co-transfection of anti-miR-381-3p and si-GFRA1 recovered the autophagy function of U2OS/DXR and MG63/DXR cells (k and A1k, l)." (PMID 33817274, 2020). "SNHG15 interference downregulated the level of GFRA1, and the co-transfection of anti-miR-381-3p and si-SNHG15 recovered the expression of GFRA1 in osteosarcoma cells." (PMID 33817274, 2020). "MiR-381-3p depletion abolished the inhibitory effects of GFRA1 interference on the proliferation and chemoresistance of osteosarcoma cells." (PMID 33817274, 2020). "Taken together, SNHG15 contributed to DXR resistance of osteosarcoma cells through the miR-381-3p/GFRA1 axis in vivo." (PMID 33817274, 2020). "SNHG15 depletion contributed to the inhibitory effect of DXR on osteosarcoma tumor growth through the miR-381-3p/GFRA1 axis in vivo." (PMID 33817274, 2020). "In summary, SNHG15 contributed to DXR resistance of osteosarcoma cells through promoting autophagy via the miR-381-3p/GFRA1 axis in vivo and in vitro." (PMID 33817274, 2020). "Taken together, GFRA1 was a direct target of miR-381-3p, and it was inversely modulated by miR-381-3p in osteosarcoma cells." (PMID 33817274, 2020). "To further illustrate the regulatory relationship among SNHG15, miR-381-3p, and GFRA1 in osteosarcoma cells, we first analyzed the linear relationship between the expression of SNHG15 and GFRA1 in DXR-resistant osteosarcoma tissues." (PMID 33817274, 2020). "We further clarified the modulatory relationship among SNHG15, miR-381-3p, and GFRA1 in osteosarcoma cells." (PMID 33817274, 2020). "The results of immunohistochemistry (IHC) also revealed that GFRA1 was notably upregulated in DXR-resistant osteosarcoma tissues compared with DXR-sensitive osteosarcoma tissues (Figure A1o)." (PMID 33817274, 2020). "Mouse xenograft studies showed that mice injected with GFRA1-overexpressing osteosarcoma cells started to develop tumors 5 days after injection and produced large-sized tumors (~90 mm3)." (PMID 29617307, 2018). "GFRA1-mediated signaling activated autophagy, resulting in hyperproliferation, cell survival and metastasis in osteosarcoma." (PMID 29617307, 2018). "GFRA1 overexpression in osteosarcoma cells significantly increased cell proliferation in the presence or absence of cisplatin with increased autophagy compared to control cells and this effect was blocked by the inhibition of autophagy." (PMID 29617307, 2018). "GFRA1-induced autophagy promoted tumor growth in mouse xenograft models, suggesting a novel function of GFRA1 in osteosarcoma chemoresistance." (PMID 29617307, 2018). "Knockdown of GFRA1 expression in osteosarcoma cells significantly increased cisplatin-induced apoptosis, while overexpression of GFRA1 reduced cisplatin-induced apoptosis." (PMID 29617307, 2018).
osteosarcoma (continued). "Recent findings show that GFRA1 can contribute to the development of chemoresistance in osteosarcoma." (PMID 29617307, 2018). "The level of GFRA1 expression was increased in two osteosarcoma cell lines, MG-63 and U-2 OS, following treatment with cisplatin at both transcriptional and translational levels." (PMID 29617307, 2018). "In addition, m6A-mediated biogenesis of circ_0032463 enhances the malignant biological behavior of osteosarcoma cells, partly by regulating the miR-145-5p/GFRA1 axis." (PMID 40707002, 2025). "These investigations suggest that GFRα1 could be a therapeutic target for the prevention of chemoresistance in osteosarcoma." (PMID 35582425, 2022). "Collectively, GFRA1 was modulated by SNHG15/miR-381-3p signaling in osteosarcoma cells." (PMID 33817274, 2020). "The SNHG15/miR-381-3p/GFRA1 axis might provide new insights into developing an effective strategy to overcome the DXR resistance of osteosarcoma cells." (PMID 33817274, 2020). "Herein, we investigated the role of GFRA1 in DXR-induced chemoresistance of osteosarcoma cells." (PMID 33817274, 2020). "MiR-381-3p was a direct target of SNHG15, and GFRA1 bound to miR-381-3p in osteosarcoma cells." (PMID 33817274, 2020). "Taken together, a further understanding of the mechanisms involving GFRA1 may provide critical information towards discovering novel potential therapeutic approaches for overcoming chemoresistance in osteosarcoma." (PMID 29617307, 2018). "Interestingly, we found that four out of nine osteosarcoma patients whose tumors were metastasized to the lung were positive for both GFRA1 and HMGB1 expression." (PMID 29617307, 2018). "Mechanistic studies showed that Src phosphorylation was increased in osteosarcoma cells with increased GFRA1 expression following cisplatin treatment and subsequently increased AMP-activated protein kinase (AMPK) phosphorylation, which is involved in the regulation of autophagy." (PMID 29617307, 2018). "However, we do not exclude the possibility that other chemotherapeutic drugs can also induce GFRA1 expression in other types of cells as well as osteosarcoma cells." (PMID 29617307, 2018). "GFRA1 expression was induced following treatment of osteosarcoma cells with the popular anticancer drug, cisplatin and induction of GFRA1 expression significantly suppressed apoptosis mediated by cisplatin in osteosarcoma cells." (PMID 29617307, 2018). "Indeed, aberrant GDNF or GFRA1 expression has been often found in various cancer cells including those of the pancreas, skin and breast, as well is in osteosarcoma." (PMID 29617307, 2018). "Moreover, our recent research with osteosarcoma demonstrated that GFRA1 promotes cell survival against the well-known anticancer agent cisplatin by promoting autophagy, a novel resistance mechanism against chemotherapy." (PMID 29617307, 2018). "Furthermore, GFRA1 expression is elevated by cisplatin treatment in osteosarcoma cells." (PMID 29617307, 2018). "Moreover, GFRA1 could reduce cisplatin-induced cell apoptosis and significantly increased osteosarcoma cell survival via autophagy." (PMID 29037220, 2017). "A positive relationship was observed between GFRA1 and SNHG15 in DXR-resistant osteosarcoma tissues." (PMID 33817274, 2020). "GFRA1 expression promotes autophagy by activating the SRC-AMPK signaling axis following cisplatin treatment, resulting in enhanced osteosarcoma cell survival." (PMID 29617307, 2018). "Correlation analysis showed a negative relationship between the levels of miR-381-3p and GFRA1 in DXR-resistant osteosarcoma tissues." (PMID 33817274, 2020). "Recently, our study demonstrated that GFRA1 induces autophagy as a novel regulatory mechanism of osteosarcoma chemoresistance; although neither ligand nor GFRA1 coreceptor were identified in this study, we found cisplatin triggers GFRA1 expression through NFκB." (PMID 29617307, 2018).
osteosarcoma (continued). "However, two other chemotherapeutic drugs that were used for osteosarcoma treatment, doxorubicin and methotrexate, did not induce GFRA1 expression, indicating that cisplatin specifically induces GFRA1 expression." (PMID 29617307, 2018). "Unlike cisplatin chemoresistance in osteosarcoma, where GFRα1 regulates autophagy independent of the proto-oncogene RET kinase 44, RET was recognized as a functional driver of BTZ resistance in osteogenic sarcoma, suggesting RET as a target for the treatment of advanced osteosarcoma." (PMID 31534554, 2019).
pancreatic cancer (9 papers, 2014 to 2022). "Overexpression of GFRα1 dramatically restores cellular growth in APE1-deficient pancreatic cancer cells treated with GDNF." (PMID 32438692, 2020). "Our previous report demonstrated that GFRA1 overexpression is associated with advanced pancreatic cancer." (PMID 29617307, 2018). "In human pancreatic cancers GFRA1 is highly expressed and associated with poorer survival." (PMID 29037220, 2017). "GFRα1 signaling in promoting invasion, metastasis, and tumor progression has been demonstrated in many different tumor types including glioma and pancreatic cancer." (PMID 35855954, 2022). "We next investigated the relationship between APE1/GFRα1 expression and clinicopathological data utilizing tissues from pancreatic cancer patients." (PMID 32438692, 2020). "We demonstrate that APE1 mediates an increase in GFRα1 expression, followed by promoting pancreatic cancer cell proliferation via the Src/ERK signaling pathway." (PMID 32438692, 2020). "In this study, we demonstrate that GDNF/GFRα1 trigger cell proliferation via the Src/ERK pathway in pancreatic cancer cells." (PMID 32438692, 2020). "Our study demonstrates that APE1 functions as a modulator of the GDNF/GFRα1/Src/ERK cascade during pancreatic cancer cell proliferation." (PMID 32438692, 2020). "Here, we demonstrate that APE1 accelerates pancreatic cancer cell proliferation through glial cell line-derived neurotrophic factor (GDNF)/glial factor receptor α1 (GFRα1)/Src/ERK axis-cascade signaling." (PMID 32438692, 2020). "We demonstrate that APE1 also stimulates pancreatic cancer cell proliferation via a GDNF/GFRα1/Src/ERK signaling pathway in this study." (PMID 32438692, 2020). "Taken together, APE1-induced GFRα1 allows pancreatic cancer cell proliferation through RET/Src/ERK cascade signaling in the response to GDNF." (PMID 32438692, 2020). "We demonstrated a novel regulatory mechanism for GDNF/GFRα1/RET/Src axis by APE1 in pancreatic cancer cell growth." (PMID 32438692, 2020). "The expression of both APE1 and GFRα1 was gradually increased as progressing pancreatic cancer grades." (PMID 32438692, 2020). "Cancer-nerve interaction studied in in vitro co-cultures of DRG and MiaPaCa-2 pancreatic cancer cells demonstrated that GFRα1 facilitates migration of cancer cells along neurites toward the center of the DRG." (PMID 29334991, 2018). "Our study showed that GFRA1 expression is regulated by nuclear factor kappa B (NFκB) in pancreatic cancer." (PMID 29617307, 2018). "In this study, we examined whether APE1-mediated regulation of GFRα1 expression has effects on pancreatic cancer cell proliferation using pancreatic cancer cells and human patient tissues, and its mechanism." (PMID 32438692, 2020). "Intriguingly, GFRα1 overexpression by GFRα1-encoded lentivirus restored GDNF-stimulated cell proliferation in APE-deficient pancreatic cancer cells, indicating that APE1 promotes GDNF-dependent pancreatic cancer cell proliferation by regulating GFRα1 expression." (PMID 32438692, 2020). "It suggests that GFRα1 regulation by APE1 can also be involved in pancreatic cancer progression." (PMID 32438692, 2020). "In addition, GDNF/GFRα1 signaling is detected in pancreatic cancers." (PMID 32438692, 2020). "RET alterations occur in ~1.9% of pancreatic cancers whereas wild-type RET, co-receptor GFRα1, and GDNF are overexpressed in 50-70% of pancreatic cancer cases." (PMID 35957881, 2022). "Our results highlight a critical role for APE1 in GDNF-induced pancreatic cancer cell proliferation through APE1/GFRα1/Src/ERK axis-cascade signaling and provide evidence for future potential therapeutic drug targets for the treatment of pancreatic cancer." (PMID 32438692, 2020). "In pancreatic cancers, GDNF/GFRα1/RET is expressed more robustly than in normal pancreatic tissue and benign tumors." (PMID 32438692, 2020). "GFRα1 and GDNF triggers Ret/Src/ERK activation, resulting in the increased growth of pancreatic cancer cells." (PMID 32438692, 2020).
pancreatic cancer (continued). "MIA PaCa-2 human pancreatic cancer cells, which contain endogenous APE1, were treated with GDNF, a binding partner of GFRα1 to investigate the effect of GDNF on pancreatic cancer cell proliferation." (PMID 32438692, 2020). "Inhibition of APE1 expression significantly suppressed GFRα1 expression in human pancreatic cancer cell lines, suggesting that APE1 is able to regulate GFRα1 expression in pancreatic cancer cells." (PMID 32438692, 2020). "The proliferation of endogenous APE1 expressed-MIA PaCa-2, a human pancreatic carcinoma cell line, was increased by treatment with GDNF, a ligand of GFRα1." (PMID 32438692, 2020). "APE1 (apurinic/apyrimidinic endodeoxynuclease 1)-induced GFRA1 protein forms a complex with RET through a lipid raft, which stimulates cell proliferation and migration in pancreatic cancer." (PMID 29617307, 2018). "According to these findings, our network revealed that ACVR2B, GFRA1, and MTHFR are the most gene transcripts that are regulated by miRNAs and their relationships to pancreatic cancer were confirmed previously." (PMID 24895587, 2014). "The miR-24 has been reported as most important miRNA and genes such as ACVR2B, GFRA1, and MTHFR are most involved in pancreatic cancer." (PMID 24895587, 2014). "In this study, we found that despite GDNF treatment, pancreatic cancer cell proliferation did not occur without GFRα1 expression which is induced by APE1." (PMID 32438692, 2020). "Taken together, these results indicate that Src may be an important intermediary between GDNF/GFRα1 and ERK signaling through APE1-mediated pancreatic cancer cell proliferation." (PMID 32438692, 2020).
gastric cancer (8 papers, 2016 to 2025). A primary or metastatic malignant neoplasm involving the stomach. "Tumor-associated macrophage-derived GDNF facilitates gastric cancer liver metastasis via GFRA1-mediated autophagy flux." (PMID 38962317, 2024). "Previous studies have demonstrated the GFRA1 methylation level was significantly decreased in gastric carcinoma with lymph/distant metastasis." (PMID 33175846, 2020). "According to a recent report, demethylation of GFRα1 is a frequent event during colorectal cancer development, and high dmGFRα1 levels can result in GFRA1 overexpression and significantly increase cancer malignancy 56; similar results were also observed in gastric cancer." (PMID 35582425, 2022). "The aberrant methylation of GFRA1 has been reported in lung cancer and gastric cancer." (PMID 27566576, 2016).
glioma (8 papers, 2016 to 2023). A benign or malignant brain and spinal cord tumor that arises from glial cells (astrocytes, oligodendrocytes, ependymal cells). "The results indicated that IBSP, MEOX2, and EPHB1 were inclined to express highly in glioma tissues compared with the adjacent relatively normal tissues, while the expression of NOG and GFRA1 tended to decrease in glioma tissues." (PMID 37501725, 2023). "IFNAR2 and PARP9 show differences across all groups, while AFP and GFRA1 are significantly differentially expressed only between other gliomas and GBM." (PMID 36834486, 2023). "Knock-down of GDNF and its binding receptor, GDNF family receptor alpha 1 (GFRA1) decreases the proliferation of C6 glioma cells." (PMID 29088765, 2017). "Studies have shown that GDNF significantly induces glioma cell proliferation and migration, while knocking down the expression of GDNF or its receptor GDNF family receptor alpha 1 (GFR alpha 1) could effectively inhibit the pathological progress of glioma." (PMID 37594930, 2023).
prostate carcinoma (8 papers, 2015 to 2022). A carcinoma that arises from epithelial cells of the prostate gland. "GFRA1 is expressed in several human cancers, such as prostate cancer and hepatocellular carcinoma, and involved in tumorigenesis through regulation of migration and invasion." (PMID 29037220, 2017). "The proliferation of prostate cancer cells and their resistance to genotoxic treatment correlate directly with the level of GFRA1 expression." (PMID 27144453, 2016). "Together, these findings indicate that prostate cancer cells expressing GFRA1 respond to GDNF stimulation with the activation of the SRC/ERK pathway and increased mitotic rates." (PMID 25575823, 2015). "There was a clear correlation between GDNF sensitivity of the prostate cancer cell lines and GFRA1 expression levels which separated the four sensitive lines from the non-responsive lines." (PMID 25575823, 2015). "Furthermore, GDNF stimulation increased the proliferation rate of prostate cancer cells and activated the signal pathway through GFRα1/SRC pathway, which was related to the expression level of GFRα1, but not related to RET." (PMID 35582425, 2022). "Specifically, GDNF (Glial Cell Derived Neurotrophic Factor) has been hypothesized to promote tumor growth and invasion in prostate cancer and its effect of resisting treatment could be related to the expression of its receptor GFRA1." (PMID 31118022, 2019). "However, the increase in RET activity within prostate cancers may also be attributed to increased secretion of GDNF by prostatic stromal cells or GFRα1 by peripheral nerves within the prostate, ultimately promoting perineural invasion of prostate cancers." (PMID 35957881, 2022). "Fibroblast GDNF exerted paracrine effects toward prostate cancer cells resulting in enhanced tumor cell proliferation and invasion, and these effects were concordant with the expression of known GDNF receptors GFRA1 and RET." (PMID 25575823, 2015). "The majority of prostate cancers expressed GFRA1 (82%) and all tumors showed RET expression, indicating that a majority of localized prostate cancers are potentially sensitive to GDNF." (PMID 25575823, 2015).
colon cancer (6 papers, 2013 to 2020). "Among these genes, GFRA1 was screened for its significant hypomethylation and high expression in invasive CRC compared to non-invasive colon cancer." (PMID 33175846, 2020). "We previously reported that APE1 regulated GFRα1 expression via NF-κB and enhanced pancreatic cell migration and neuronal cell survival, and it also participated in JAGGED1/Notch signaling in colon cancer progression by regulating Egr-1." (PMID 32438692, 2020). "Interestingly, ARTN, NRTN, GFRα1, and GFRα3 are found in colon tumors, potentially arising from gut nerves or associated with chronic inflammation of the intestine, which increases cancer risk, suggesting a subset of RET-expressing colon tumors may be responsive to GFL stimulation." (PMID 30666215, 2018). "Therefore, although TF E2F7 display opposite regulation effect on GFRA1 when comparing with NR3C2 and NR3C1, it did not have a competitive role with them in colon cancer." (PMID 32849837, 2020).